EGFR (epidermal growth factor receptor)
Diseases named in the same sentence as EGFR in open-access papers (continued):
Sharing a sentence is not in itself a finding about the gene and the disease.
lung cancer (continued). "Moreover, a meta-analysis of 16 trials on EGFR TKI treatment in lung cancer patients showed that pneumonia is the most common cause of death related to EGFR TKI toxicity." (PMID 40071087, 2025). "Similarly, the combination of osimertinib and the HER2 ADC trastuzumab emtansine (TDM1) was able to prevent or delay osimertinib resistance in preclinical models of EGFR-mutated lung cancer." (PMID 40243603, 2025). "In lung cancer, the most frequent oncogene mutation occurs on the epidermal growth factor receptor (EGFR) gene, which results in overexpression in up to 80% of NSCLC cases, with Ki‐ras2 Kirsten rat sarcoma viral oncogene homologue (Kras) being the most common oncogene‐driven subtype of LUAD." (PMID 39592417, 2025). "Besides, a recent study shows that KMT5C loss can induce EGFR inhibitor resistance in lung cancer, but the function of KMT5C in lung cancer progression is unexplored." (PMID 40126333, 2025). "Additionally, the prevalence of EGFR mutations, which are highly associated with lung cancer, is higher in women." (PMID 39916713, 2025). "Additionally, the model identified key cytological characteristics, including a unique feature associated with EGFR mutations, highlighting its potential to support precision medicine in lung cancer care." (PMID 40001695, 2025). "In the field of lung cancer diagnosis and treatment, genetic testing of lung percutaneous biopsy samples is mainly used to evaluate the value of targeted drug use, such as detecting gene mutations such as EGFR and K-RAS." (PMID 40777114, 2025). "In addition to the alterations in the EGFR, that, like the mutations of K-Ras, are predominantly found in adenocarcinoma, in other lung cancer entities, FGFR1 amplifications are identified frequently." (PMID 40806483, 2025). "Lung cancer treatment has changed in the last twenty years since the discovery of EGFR mutations." (PMID 40136350, 2025). "Similarly, primary EGFR‐mutated lung cancer cells (MGH119) showed higher CEACAM5 and epithelial marker CLDN1 expression but lower mesenchymal marker CDH2 expression than their EGFR‐TKI gefitinib‐resistant counterparts (MGH119GR)." (PMID 40856433, 2025). "Indeed, in our study, we verified that targeting c-kit attenuated stemness of gefitinib resistant lung cancer cells and sensitized these cells to gefitinib treatment due to the persistent presence of EGFR 19del mutation." (PMID 39744423, 2025). "Consequently, there is a need for a detailed analysis of clinical outcomes, based on clinicopathologic characteristics and genetic alterations, in patients with resected EGFR‐mutated lung cancer." (PMID 39757012, 2025). "Moreover, multiple studies have revealed that lung cancer in non-smokers differs on a genomic and molecular level from smoking-related lung cancer, characterized by an enrichment of targetable oncogenic alterations (such as EGFR mutations)." (PMID 40517166, 2025). "Based on these findings, we hypothesize that missense mutations in NTRK1 and ZRSR2 may contribute to primary resistance to Osimertinib in non‐small cell lung cancer (NSCLC) with EGFR mutations through modulation of the PI3K pathway." (PMID 39907312, 2025). "The selective and potent EGFR degraders with low molecular weights reported here may serve as lead compounds for treating EGFR mutation-related diseases, such as lung cancer." (PMID 41208859, 2025). "The results of the Cox regression model revealed that lower HDL cholesterol levels were associated with a greater risk of overall lung cancer (1.11 [1.08–1.15]), adenocarcinoma (1.08 [1.04–1.12]), squamous cell carcinoma (1.21 [1.12–1.31]) and EGFR-mutated lung cancer (1.13 [1.08–1.20])." (PMID 39883280, 2025).
lung cancer (continued). "Consistent with previous quantitative shape analysis, our findings revealed that EGFR-mutated lung carcinoma exhibited significantly higher sphericity indices than wild-type tumors, providing an additional morphological biomarker for predicting EGFR mutation status." (PMID 41415549, 2025). "SMARCB1-deficient lung carcinomas (INI1 loss) rarely exhibit EGFR mutations." (PMID 40291911, 2025). "In contrast, DUSP22 deletion enhances HCC827 cell sensitivity to gefitinib, suggesting that DUSP22 loss promotes EGFR dependence in lung cancer, and targeting EGFR could be a more effective therapeutic approach for DUSP22-deficient lung tumors." (PMID 38877005, 2024). "Mutation analysis of 12 lung cancer patients showed that EGFR mutations, including three Exon19del, three L858R, and six wild types, were detected in 12 CTC samples, whereas five Exon19del, three L858R, and four wild types were detected in the corresponding 12 tumor tissue samples." (PMID 39335743, 2024). "constructed a radiomic model may aid in predicting the acquired drug‐resistant mutation T790M following targeted therapy for lung cancer, suggesting the potential application of radiogenomic models in optimizing EGFR‐targeted therapy decisions." (PMID 39252824, 2024). "However, the disease was successfully managed with Osimertinib, a drug known for its ability to effectively penetrate the central nervous system in patients with EGFR‐mutated non‐small cell lung cancer." (PMID 38993692, 2024). "In lung cancer, a new parameter called "intratumor metabolic and heterogeneity factor" was tested, and it has been reported to be useful in predicting epidermal growth factor receptor (EGFR) mutations." (PMID 39320419, 2024). "EGFR mutations, which are common in certain types of lung cancer, may be associated with E5 activity; these mutations were more prevalent in lung adenocarcinomas harboring HPV DNA." (PMID 39599846, 2024). "Notably, in a molecular testing cohort of 38 LC patients, 84.2% of lung cancer cases exhibited driver mutations, in which EGFR mutations frequence prevalent was 74.2%." (PMID 38402182, 2024). "EGFR germline mutations have been detected in families with a history of lung adenocarcinoma, offering potential insights into the risk and carcinogenic mechanisms of lung cancer." (PMID 39160638, 2024). "Therefore, EGFR mutation showed a clear association with increased TAP levels during the early diagnosis stage of lung cancer." (PMID 38980474, 2024). "Similarly, CTCs from lung cancer patients with EGFR mutations can predict the response to EGFR-targeted TKIs like gefitinib (Iressa)." (PMID 38398206, 2024). "Women are more often predisposed to lung cancer mutations (EGFR) and rearrangements (ALK, BRAF)." (PMID 38592288, 2024). "Finally, future research should delve into the relationship between the quantitative parameters of DLCT and the efficacy of targeted treatments in lung cancer patients harboring EGFR mutations." (PMID 38679659, 2024). "However, data from pathology reports are used in routine clinical practice, and common mutations such as EGFR in lung cancer and ESR1 or PIK3CA mutations in breast or colon cancer are not present on the molecular board." (PMID 39457104, 2024). "The results of our preliminary study showed that the dynamic metabolic parameter Ki has a better differential diagnostic value in lung cancer differential diagnosis (cutoff value of 0.0250 ml/g/min) and EGFR status prediction (cutoff value of 0.0350 ml/g/min), especially improved specificity." (PMID 39078558, 2024).
lung cancer (continued). "For example, in the sentence ‘The EGFR gene has been associated with increased risk of lung cancer’, the RE system may recognise the association between the EGFR gene and lung cancer as ‘connected to increased risk’." (PMID 39588066, 2024). "Secondly, the detection of specific mutations such as EGFR T790M, R776H, or V843I during pre-treatment genotyping for lung cancer may indicate a possible germline mutation." (PMID 39160638, 2024). "Similarly, in a cohort of 1039 Asian patients with mostly advanced-stage lung cancer, fewer patients aged ≤50 years had EGFR mutations than older patients (57.8% vs. 66.1%)." (PMID 39722087, 2024). "Previous studies have suggested that loss of the EGFR T790M gene mutation may contribute to the development of resistance to Osimertinib in non‐small cell lung cancer (NSCLC)." (PMID 38584122, 2024). "However, in lung cancer patients with EGFR mutations, a higher TMB is associated with a poorer response to targeted therapy." (PMID 38319706, 2024). "Additionally, EGFR is a targetable mutation in some lung cancers, and treatment with EGFR-targeted antibodies confer significant improvement in survival." (PMID 38592275, 2024). "Consistent with previous studies, EGFR was the most commonly mutated gene in lung cancer." (PMID 38313018, 2024). "We then divided the patients into four subgroups based on their CD151 levels and whether they had mutations in the EGFR gene, which is often altered in lung cancer." (PMID 38982031, 2024). "Future studies could also expand the scope beyond genetic features to additionally include immunologic characteristics, whose particular characteristics and role in pathogenesis and treatment of EGFR‐mutated lung cancer are increasingly recognized." (PMID 38284983, 2024). "Furthermore, statins can overcome EGFR-TKI resistance in patients with lung cancer harboring KRAS mutation, and they provided an increased response rate in lung cancer patients previously treated with nivolumab." (PMID 38478558, 2024). "EGFR variants were highly expressed among lung cancer patients." (PMID 38245692, 2024). "Recent studies suggest that anti-apoptotic molecules such as BCL-XL and MCL1 may function in DTP formation in EGFR-mutated lung cancer." (PMID 39122703, 2024). "Consequently, these results suggest that the duration of EGFR-TKI treatment is more important than the administration of ICI for a survival benefit in patients with EGFR mutated lung cancers." (PMID 38347279, 2024). "Peer-reviewed articles from the last ten years were selected using the combination of the following keywords: “lung cancer genetics”, “targeted therapy lung cancer”, “EGFR mutations”, “ALK rearrangements”, and “immune checkpoint inhibitors”, without any restriction." (PMID 39199653, 2024). "Moreover, DECT has potential value in predicting EGFR mutation status in lung cancer, with AUCs ranging from 0.702 to 0.760." (PMID 38679659, 2024). "The potential role of alternative ADCs targeting the human trophoblast cell‐surface antigen 2 (TROP2) (NCT04152499) and MET351, 352 (NCT03859752) is also being evaluated in patients with lung cancers, potentially including NSCLCs with EGFR mutations or ALK rearrangements." (PMID 39184861, 2024). "Given that our cohort consisted of early‐stage lung cancer, we aimed to investigate the comparability of EGFR mutation frequency as a reference point by comparing the WES data of nonsmokers in our current cohort (early stage, MIA/IA) with the CHOICE cohort (late‐stage)." (PMID 39036344, 2024). "For example, the detection of a secondary mutation in the epidermal growth factor receptor (EGFR) gene in lung cancer patients who initially responded to EGFR inhibitors but then relapsed can guide the switch to alternative therapies designed to overcome resistance." (PMID 39045325, 2024). "The EGFR is implicated in the carcinogenesis of different types of cancer, such as lung cancer." (PMID 38473984, 2024).
lung cancer (continued). "In addition, we want to explore the value of each metabolic parameter in predicting the type of lung cancer pathology and EGFR mutations." (PMID 38730287, 2024). "Although CD155 was not significantly correlated with PD-L1 expression in the entire population, CD155high was associated with higher PD-L1 positivity in the oncogene-mutated subsets (ALK and EGFR alterations), which is concordant with studies in early-stage lung cancer." (PMID 39267111, 2024). "Additionally, abundant epidermal growth factor receptor (EGFR) mutations have been detected in EVs isolated from the serum or bronchoalveolar lavage fluid of lung cancer patients." (PMID 39062561, 2024). "The EGFR‐driven group (Group 1) exhibits a lack of T cell infiltration, especially CD8 T cell infiltration, which is consistent with the clinical observation that lung cancer patients with EGFR mutation tend to have an unfavorable response to PD‐1/PD‐L1 checkpoint inhibitors." (PMID 39036344, 2024). "However, there are reciprocal examples where we find EGFR extracellular domain mutations in lung cancer and kinase domain mutations in glioblastoma." (PMID 38548752, 2024). "Clinical trials for these drugs revealed tumor shrinkage only in a small subset of lung cancer patients, and subsequent analysis of tumor tissues obtained from the responders identified unknown drug-sensitizing EGFR mutations." (PMID 38612902, 2024). "Manifestation of secondary mutations such as T790M and C797S, stimulation of another signaling pathway like Met, downstream pathway deviation like AKT mutations, and EGFR-TKIs-mediated apoptotic pathway disruption are the mechanisms that make lung cancer cells resistant to TKIs." (PMID 38234663, 2024). "A protocol is presented for a national whole-of-patient-population retrospective cohort study designed to describe the safety and effectiveness of erlotinib and gefitinib during their first decade of routine use in NZ for treating EGFR mutation–positive lung cancer." (PMID 38954434, 2024). "EGFR mutations occur more commonly in lung cancer and glioma." (PMID 39054543, 2024). "Epidermal growth factor receptor (EGFR) tyrosine kinase inhibitors (TKIs) have revolutionized the treatment of advanced EGFR‐mutated non‐small cell lung cancer (NSCLC) with prolonged overall survival (OS) compared with platinum‐based doublet chemotherapy in several phase III trials." (PMID 38284983, 2024). "Among gene-specific susceptibility for lung cancer, EGFR-associated one needs a special mention." (PMID 39085889, 2024). "Consequently, the quest to enable the predominant group of lung cancer patients who harbor EGFR mutations to benefit from immunotherapy remains a challenging pursuit." (PMID 39062533, 2024). "Second, lung cancer with ex20ins mutation in the helical region (p.A763_Y764insFQEA) cannot be assessed by the cobas test, and patients with helical region mutations are responsive to traditional EGFR-TKIs." (PMID 38687753, 2024). "Moreover, emerging biomarkers are used to assess genetic predispositions (BRCA mutations) and guide treatment options (human EGFR 2 in breast cancer and EGFR in lung cancer)." (PMID 39767566, 2024). "The timeline views demonstrated that the references can be categorized into 8 clusters: lower-grade glioma, lung cancer histology, lung adenocarcinoma, breast cancer, radiation-induced lung injury, epidermal growth factor receptor mutation, late radiotherapy toxicity, and artificial intelligence." (PMID 38980713, 2024). "Recently, various DTP cell markers have been reported to function in or mediate EGFR-TKI resistance in EGFR-mutated lung cancer, and these could, therefore, serve as novel therapeutic targets." (PMID 39122703, 2024). "The epidermal growth factor receptor gene is the most commonly mutated gene in lung cancer (EGFR)." (PMID 38783639, 2024).
lung cancer (continued). "In addition, EGFR mutations are often directly or indirectly associated with the pathogenesis of some cancers with high global morbidity and mortality, such as lung cancer, pancreatic cancer and head and neck cancer." (PMID 38298194, 2024). "We have shown that multiple primary EGFR-mutant lung cancers may arise from canonical activating EGFR mutations that are acquired early in development, leading to mosaicism for this driver mutation in the adult lung." (PMID 39406916, 2024). "In lung cancer with EGFR Exon 20 insertion mutations, brain metastases present a significant challenge, with studies like CHRYSALIS only including patients with previously treated asymptomatic brain metastases, showing varying rates of intracranial progression." (PMID 38892105, 2024). "However, due to resource constraints, our study only considered testing for the two most common EGFR mutations (Exon 19 deletion and Exon 21 L858R) in our cohort of patients with primary lung cancers, which was a limitation of our study." (PMID 39429333, 2024). "For example, tamoxifen, an FDA-approved inhibitor of the protein kinase C genes PRKCB and PRKCE, currently used for breast cancer treatment, could potentially be used to target EGFR or KRAS-mutated lung cancers and NRAS-mutated skin cancer." (PMID 37863651, 2024). "It has been established that PM2.5 exposure levels are associated with EGFR‐driven lung cancer." (PMID 39315583, 2024). "EGFR is targetable using tyrosine kinase inhibitors (TKIs) that bind to the active site and prevent downstream signaling, and first-generation TKIs are clinically approved for first-line treatment for lung cancers with known EGFR mutations." (PMID 38538642, 2024). "On the other hand, phase I clinical trials of osimertinib combined with ABT-263 (Navitoclax) for patients with EGFR-mutated lung cancer after EGFR-TKI failure have been conducted, and dosing of osimertinib 80 mg daily and navitoclax 150 mg daily was well tolerated." (PMID 39122703, 2024). "Consequently, classical EGFR-TKI drugs are ineffective in lung cancer patients with EGFR ex20ins, and the low recurrence of EGFR ex20ins mutations." (PMID 38774882, 2024). "Given this, we sought to understand whether lung cancer cells expressing our panel of uncharacterized EGFR extracellular domain variants could have functionality in the presence of afatinib or dacomitinib." (PMID 38548752, 2024). "By identifying specific genetic mutations or protein expressions in lung cancer cells, clinicians can prescribe treatments that are more likely to be effective for the individual patient, such as tyrosine kinase inhibitors for patients with EGFR mutations." (PMID 39195131, 2024). "Before their introduction, clinical trials of erlotinib and gefitinib had demonstrated substantial therapeutic benefits in patients with EGFR mutation–positive lung cancer, with >50% reduction in the risk of disease progression in pooled analyses of randomized trials." (PMID 38954434, 2024). "In this study, we perform scRNA-seq to analyze gene expression profiles, including those of apoptosis-related genes, and their response to treatment in EGFR-mutated lung cancer using human clinical samples and cell lines and also perform ST analyses using transgenic mouse specimens." (PMID 39122703, 2024). "This study aimed to examine the clinical characteristics of bone metastasis (BoM) in patients with non‐small cell lung cancer (NSCLC) who have an epidermal growth factor receptor (EGFR) mutation and to identify the most effective treatment strategy using EGFR–tyrosine kinase inhibitors (TKIs)." (PMID 38549499, 2024). "In addition, the meta-analysis investigating the correlation of PD-L1 expression with EGFR mutations in lung cancer showed that high PD-L1 expression was associated with EGFR mutations." (PMID 39112802, 2024).